IL27 (interleukin 27)
Diseases named in the same sentence as IL27 in open-access papers (continued):
Sharing a sentence is not in itself a finding about the gene and the disease.
rheumatoid arthritis (continued). "Dysregulation of IL-27 concentrations and their correlation with autoimmune parameters have also been shown to relate to the immunopathogenesis of Th1/Th17-mediated inflammatory diseases, such as rheumatoid arthritis, multiple sclerosis, inflammatory bowel disease, and Behçet’s disease (BD)." (PMID 39766196, 2024). "This means that rheumatoid arthritis might be a crucial source of IL-27 in RA." (PMID 35058928, 2021). "Therefore, IL-27 may trigger inflammation in different diseases, including rheumatoid arthritis (RA) and inflammatory bowel disease (IBD)." (PMID 34744512, 2021). "Alteration in the concentration of IL-27 and its correlation with autoimmune parameters have also been reported in several Th1/Th17-mediated inflammatory disorders, such as multiple sclerosis, systemic lupus erythematosus, inflammatory bowel disease, and rheumatoid arthritis." (PMID 32616337, 2020). "Related to its suppressive affects on Th17 cells it has been recently shown that IL-27 can ameliorate inflammation and pathology associated with experimental autoimmune encephalomyelitis (EAE) and collagen induced arthritis (CIA), murine models of multiple sclerosis and rheumatoid arthritis." (PMID 22479310, 2012). "IL-23 and IL-27 represent additional cytokines of interest in rheumatoid arthritis (RA)." (PMID 25561237, 2014). "Furthermore, various reports suggest a potential immunopathological role of IL-27 in chronic inflammatory diseases, including chronic CHIKV-dependent arthritis, and rheumatoid arthritis." (PMID 38720890, 2024). "In rheumatoid arthritis, increased IL-27 levels in the joint synovial fluid but not in the blood have been reported." (PMID 28738904, 2017). "However, the level of IL-27 in rheumatoid nodules was studied only by one research group, and there is no greater independent evidence to document this." (PMID 35058928, 2021). "IL-27 is a multifunctional immune regulatory factor, which is differentially regulated in multiple sclerosis/experimental autoimmune encephalomyelitis (EAE), inflammatory bowel disease (IBD), rheumatoid arthritis (RA) and other immune diseases, and plays a pro-inflammatory or anti-inflammatory role." (PMID 38117410, 2024).
melanoma (34 papers, 2010 to 2025). A malignant, usually aggressive tumor composed of atypical, neoplastic melanocytes. "In melanoma, new markers are continuously exposed through bioinformatics technologies, and multiple markers including IL27, CXCL8, THBS1, and KIT have been identified to be associated with melanoma metastasis and treatment outcomes." (PMID 36438905, 2022). "To reexamine the effects of IL27 on therapeutic responses, we investigated the association of IL27 expression with the IC50 of a vast range of agents in various melanoma cell lines using data from CTRP and CCLE." (PMID 34733272, 2021). "Immune cell independent effects were also suggested when IL-27 inhibited the growth of subcutaneously implanted B16-F10 melanomas, in wildtype (WT) as well as IFNγ-deficient or NOD-SCID mice." (PMID 31637217, 2019). "Furthermore, IL27 was significantly associated with hot tumor state, multiple predictors of response to immunotherapy, and improved drug response in patients with melanoma." (PMID 34733272, 2021). "Consistent with our speculation that programmed cell death occurs in tumor cells, we have previously demonstrated that high IL27 expression indeed is associated with elevated immune response and improved survival in melanoma." (PMID 34733272, 2021). "Moreover, IL27 was markedly higher in 38 patients who benefited from radiotherapy than that in 321 counterparts who resisted it (t-test; P = 0.038), suggesting that IL27 may be linked to response to melanoma therapy." (PMID 34733272, 2021). "For instance, MDSCs induce reprogramming of TAMs by suppressing CD40/IL-27 signals to promote melanoma progression in systemic lupus erythematosus mice." (PMID 40453088, 2025). "Other studies have shown that in melanoma patients, IL27 is closely related to CD8+ cells, and is related to the treatment effect and prognosis of patients." (PMID 36341437, 2022). "Accordingly, results obtained in murine models of plasmacytoma, melanoma, and neuroblastoma showed that both systemic and intratumorally delivered IL-27 enhanced presence of CD8+ CTLs in tumor microenvironment which resulted in the tumor regression." (PMID 35757015, 2022). "Exosomes from antigen-stimulated RBL2H3 cells enhanced invasion of B16F1 melanoma cells in an IL-27-dependemt manner." (PMID 34234781, 2021). "We found that exosomes of antigen-stimulated RBL2H3 cells enhanced the invasion of B16F1 melanoma cells and induced M2 macrophages polarization in an IL-27-dependent manner." (PMID 34234781, 2021). "IL-27 inhibits the proliferation of B16 melanoma transfectants expressing IL-27R by augmenting the expression of IRF-180." (PMID 34045653, 2021). "To date, very limited research has been carried out regarding the relationship between IL27 and melanoma." (PMID 34733272, 2021). "Although we demonstrated that IL27 is predictive of favorable survival in the TCGA cohort, we wondered if the prognostic value of IL 27 was also valid in other melanoma cohorts." (PMID 34733272, 2021). "Given the controversial roles of IL27, this study aimed to clarify the association of IL27 with prognosis, TME, and immunotherapy in melanoma." (PMID 34733272, 2021). "To investigate the clinical relevance of IL27, we analyzed RNA-seq data and clinical information from the TCGA cohort of 470 patients with melanoma." (PMID 34733272, 2021). "B16F10 melanoma cells that express single chain IL-27 exerts anti-angiogenic and antitumor activity." (PMID 34234781, 2021). "To investigate the prognostic value of IL27 in different cohorts, we investigated its prognostic relevance in five melanoma cohorts (viz." (PMID 34733272, 2021). "Further analysis suggested that IL27 was implicated in TME and programmed cell death including pyroptosis, autophagy and apoptosis in melanoma." (PMID 34733272, 2021). "Similar studies reported pro-tumorigenic action of IL-27 favoring the expansion of Treg cells, where IL-27R−/− Treg cells were unable to suppress anti-tumor immunity in mouse models of melanoma." (PMID 33418929, 2021).
melanoma (continued). "To comprehensively characterize the effects of IL27 expression on immune cells, we first estimated the abundance of each immune cell using ssGSEA based on RNA-seq data from the TCGA cohort of melanoma patients." (PMID 34733272, 2021). "Our findings would contribute to uncovering the multifaceted roles of IL27 and provide evidence for future cytokine-based immunotherapy against melanoma." (PMID 34733272, 2021). "For example, IL-27 has direct anti-proliferative effects on both mouse and human melanoma cells in a STAT1 dependent manner." (PMID 31681561, 2019). "Only one study demonstrated that IL-27 reduced tumor angiogenesis in a melanoma model and an in vivo angiogenesis assay." (PMID 31637217, 2019). "The ability of IL-27 to enhance NK cell mediated killing of cancer cells has been demonstrated in a series of murine models including hepatocellular carcinoma, melanoma, head and neck squamous cell carcinoma." (PMID 31681561, 2019). "IL-27 expression correlated with that of PD-L1 and IL-10 in melanoma samples, and IL-27 induced IL-10 and PD-L1 expression in melanoma cells in vitro." (PMID 28255204, 2017). "Another study reported that inhibition of human melanoma cells by IL-27 involved induction of TRAIL expression." (PMID 28255204, 2017). "Yoshimoto proposed that IL-27 had an antiproliferative effect on melanomas through WSX-1/STAT1 signalling." (PMID 26932661, 2016). "In the same series of tumors, stronger IL-27 staining was found in advanced thick melanomas and correlated with PDL-1 and IL-10 expression." (PMID 26218530, 2015). "Yoshimoto et al23 discovered that IL-27 was able to perform direct antiproliferative effects on several WSX-1-positive human melanoma lines." (PMID 25170932, 2014). "In various murine tumor models including melanoma models, ectopic expression of IL-27 has been shown to play an anti-tumoral role and to favor tumor regression." (PMID 24130734, 2013). "Three human melanoma cell lines were treated with IL-27 and/or poly(I:C) for 72–96 h and their proliferative responses were determined." (PMID 24155891, 2013). "Either IL-27 or poly(I:C) alone slightly reduced tumor growth but their combination more strongly inhibited tumor growth in the three melanoma cell lines." (PMID 24155891, 2013). "From among three human melanoma cell lines, SK-MEL-37 cells were used, because this cell line appears to be most susceptible to the treatment with IL-27 or combined IL-27 and poly(I:C)." (PMID 24155891, 2013). "We found that IL-27 inhibits in vitro tumor growth of human melanomas and greatly enhances the expression of TNF-related apoptosis inducing ligand (TRAIL) in a dose-dependent manner." (PMID 24155891, 2013). "Of note, regardless of the expression levels of TRAIL, the treatment with anti-TRAIL neutralizing Ab, but not control Ab, partly but significantly abrogated the inhibitory effect on tumor growth of combined IL-27 and poly(I:C) in all three melanoma cell lines." (PMID 24155891, 2013). "Recently, a member of the IL-12 family, IL-27, has been proposed as a candidate for anti-tumoral therapy, notably in melanoma." (PMID 24130734, 2013). "In the present study, we attempted to gain a better understanding of the molecular events governing the anti-proliferative effect of IL-27 on melanomas." (PMID 24155891, 2013). "Taken together, the present results suggest that IL-27 exerts anti-proliferative activity against human melanomas by mechanisms similar to those of IFN-α in a STAT1/IRF-1–dependent manner and partly in a TRAIL-dependent manner." (PMID 24155891, 2013). "To gain a better understanding of the molecular events governing the anti-proliferative effect of IL-27 on melanomas, we first focused on TRAIL, which is an important immune effector molecule in the surveillance and elimination of developing tumors." (PMID 24155891, 2013).
melanoma (continued). "To evidence a possible correlation between IL-10 and IL-27 expression in melanoma lesions, we analyzed by immunohistochemistry IL-10 expression in 43 cases of primary cutaneous or metastatic melanoma." (PMID 24130734, 2013). "Among three human melanoma cell lines used in this study, SK-MEL-13 showed slightly less susceptibility to the IL-27 and poly(I:C)–mediated TRAIL-dependent growth inhibition and SK-MEL-37 showed more susceptibility to it." (PMID 24155891, 2013). "Consistent with the previous results, IL-27 induced IRF-1 expression at the mRNA level in all three human melanomas." (PMID 24155891, 2013). "It has been shown that anti-tumor and anti-angiogenic activities of IL-27 in murine melanoma tumors." (PMID 24274066, 2013). "Three human melanoma cell lines were then stimulated with increasing doses of IL-27, and total RNA was extracted 24 h later and subjected to RT-PCR analysis." (PMID 24155891, 2013). "In the present study, we further explored the molecular mechanism whereby IL-27 induces direct suppression of tumor growth of human melanomas." (PMID 24155891, 2013). "The antitumor effects of IL-27 against poorly immunogenic tumors such as B16F10 melanoma are mediated by various mechanisms through NK cells, angiogenesis, and its direct effects on tumors." (PMID 20885915, 2010). "IL-27 also possesses potent antiangiogenic activity on melanomas as does IFN-γ, which contributes to its antitumor and antimetastatic activities." (PMID 20885915, 2010). "Thus, preventing the reprogramming of macrophages induced by inhibition of CD40/IL-27 signals shows potential as a precise immunotherapeutic strategy in melanoma.As specific components of myeloid origin, platelets can also affect macrophage polarization." (PMID 40453088, 2025). "The role of IL-27 in melanoma progression needs to be studied further." (PMID 38719996, 2024). "We also showed that IL-27 can be used at low doses as a potent adjuvant in combination with LyUV or γ-irradiation treated cancer cells to improve the protection provided by a prophylactic cancer vaccine in a mouse melanoma model." (PMID 35529885, 2022). "Although early literature shows that IL27 may have potential anti-melanoma effects by promoting the activity of CD8+ T cells, there is still a lack of specific molecular mechanisms underlying the impact of IL27 on CD8+ T cells." (PMID 34733272, 2021). "Moreover, we reexamined the role of IL27 expression on T cell infiltration using GSEA based on RNA-seq data of melanoma patients from the TCGA cohort." (PMID 34733272, 2021). "First, we found that IL27 had a critical clinical relevance, and could serve as a predictor of survival in patients with melanoma." (PMID 34733272, 2021). "PSA enhanced the metastatic potential of mouse melanoma B16F1 cells in an IL-27-dependent manner." (PMID 34234781, 2021). "In conclusion, IL27 was considered a predictor of survival outcomes in patients with melanoma." (PMID 34733272, 2021). "IL27 is reported as a protumor cytokine in pancreatic cancer and hepatocellular carcinoma, whereas considered as an antitumor factor in lung cancer and melanoma." (PMID 34733272, 2021). "They found that IL-27 might induce suppressive molecules such as PD-L1 and IL-10 and thus immunosuppressive responses and melanoma progression." (PMID 30581461, 2018). "In addition, a combination of IL-27 with the TLR3 ligand poly (I:C) cooperatively suppressed melanoma growth in xenograft models." (PMID 28255204, 2017). "Also, the antitumor activity of IL-27 was partially inhibited by an anti-CXCL10 antibody in the B16F10 melanoma model." (PMID 28255204, 2017). "Also, WSX1-negative B16F10 mouse melanoma cells became sensitive to IL-27 antiproliferative activity upon WSX1 transfection, whereas transfection of a mutant WSX1 unable to recruit STAT1 was ineffective." (PMID 28255204, 2017). "IL-27 expressed by gene transfer in B16F10 melanoma may exert antiangiogenic functions on subcutaneous tumors and lung metastases." (PMID 28255204, 2017).
melanoma (continued). "Moreover, IL-27 and poly(I:C) cooperatively suppressed in vivo tumor growth of human melanoma in immunodeficient mice." (PMID 24155891, 2013). "Moreover, it was recently demonstrated that IL-27 inhibits the growth of human tumors including melanoma, multiple myeloma, B-acute lymphoblastic leukemia, follicular lymphoma, diffuse large B-cell lymphoma, and acute myeloid leukemia." (PMID 24155891, 2013). "In this study, we investigated whether IL-27 might play a role in the development of melanoma in humans." (PMID 24130734, 2013). "In the present study, we have explored the effect of IL-27 on human melanomas and uncovered a previously unknown mechanism." (PMID 24155891, 2013). "Consistent with this hypothesis, we found that IL-27 could induce suppressive molecules such as PD-L1, and to a lesser extent IL-10, in melanoma cells, and that the in situ expression of IL-27 in melanoma correlated with those of PD-L1 and IL-10." (PMID 24130734, 2013). "We next investigated whether PD-L1 expression by melanoma cells correlated with IL-27 expression by tumor cells in situ." (PMID 24130734, 2013). "Furthermore, the combination of IL-27 and poly(I:C) significantly suppressed in vivo tumor progression in the human melanoma xenograft model using immunodeficient NOD/SCID mice." (PMID 24155891, 2013). "In this study, we show that tumor cells in melanoma can co-express both subunits of IL-27." (PMID 24130734, 2013). "However, B16F10 cells transfected with WSX-1-expression vector (B16F10-WSX-1) become as responsive to IL-27 as several human melanomas." (PMID 24155891, 2013). "Because IL-27 expression in melanoma appeared to correlate with tumor progression, we investigated by which mechanisms IL-27 could favor melanoma progression." (PMID 24130734, 2013). "Taken together with the present results, it is highly conceivable that IL-27–induced up-regulation of TRAIL in human melanomas could be also mediated by STAT1/IRF-1 signaling." (PMID 24155891, 2013). "Pre-treatment with IL-27 resulted in lower IL-2 production in the co-culture that was specifically reversed by addition of an anti-PD-L1 neutralizing Ab, indicating that PD-L1 induction by IL-27 on melanoma cells decreased T-cell activation as expected." (PMID 24130734, 2013). "Moreover, the induction of IRF-1 was revealed to contribute to the IL-27–mediated inhibition of tumor growth of B16F10 melanoma." (PMID 24155891, 2013). "Whether endogenous IL-27 plays a physiological role in the development of human melanoma is unknown." (PMID 24130734, 2013). "In addition, we recently demonstrated that IL-27 has anti-proliferative activity and acts directly on melanomas through WSX-1/STAT1 signaling." (PMID 24155891, 2013). "These in situ data suggested that the immunosuppressive functions of IL-27 may dominate in human melanoma." (PMID 24130734, 2013). "At the protein level, IL-27 also enhanced the expression of TRAIL, which was detected by Western blot analysis (see the later section), but these melanomas only slightly expressed cell surface TRAIL in response to IL-27, which was detected by fluorescence-activated cell sorter (FACS) analysis." (PMID 24155891, 2013). "This induction was confirmed by FACS analysis in melanoma cells stimulated for 15 hrs with IL-27." (PMID 24130734, 2013). "Altogether, our data question the use of recombinant IL-27 in anti-melanoma therapy in humans." (PMID 24130734, 2013). "IL-27 also possesses potent direct antiproliferative activity on melanomas as does IFN-γ." (PMID 20885915, 2010). "To confirm the hypothesis that the effect of IL27 could be offset by drug resistance following medication, we analyzed its prognostic value using RNA-seq data and survival data of melanoma patients from GSE50509 cohort who had received dabrafenib or vemurafenib treatment." (PMID 34733272, 2021). "Next, we wondered whether IL27 could serve as an independent predictor of survival in melanoma." (PMID 34733272, 2021).